RNU6-1095P (RNA, U6 small nuclear 1095, pseudogene)
Gene: Small nuclear RNA gene on chromosome 10 (11,923,181 to 11,923,288, forward strand). Ensembl gene ENSG00000251957.
Homologues: Orthologues: chimpanzee U6 (98% identical), guinea pig U6 (75% identical), dog U6 (73% identical), mouse Gm22805 (73% identical), rabbit U6 (69% identical). Paralogues in human: RNU6-1060P (81% identical), RNU6-1222P (81% identical), RNU6-24P (81% identical), RNU6-140P (80% identical), RNU6-14P (80% identical), RNU6-19P (80% identical), RNU6-31P (80% identical), RNU6-48P (80% identical), RNU6-1124P (79% identical), RNU6-1152P (79% identical), RNU6-12P (79% identical), RNU6-1303P (79% identical), and 1287 more.